ABCC3 (ATP binding cassette subfamily C member 3)
Diseases named in the same sentence as ABCC3 in open-access papers (continued):
Sharing a sentence is not in itself a finding about the gene and the disease.
glioma (32 papers, 2010 to 2024). A benign or malignant brain and spinal cord tumor that arises from glial cells (astrocytes, oligodendrocytes, ependymal cells). "Notably, ABCC3 was closely linked to glioma heterogeneity, low-risk group had more responders than the high-risk group, and low-risk patients had better overall survival." (PMID 35936006, 2022). "Next, we verified whether the knockdown of ABCC3 was associated with the increased sensitivity of glioma cells to arsenic trioxide." (PMID 36091778, 2022). "Moreover, ABCC3 exacerbated glioma proliferation and was associated with temozolomide (TMZ) resistance." (PMID 35936006, 2022). "Moreover, our team also studied the association between ABCC3 expression and clinical features of glioma patients, finding that differential expression of ABCC3 was remarkably related to age, 1p19q codeletion, PRS type, chemo status, grade, IDH mutation state, and histology." (PMID 34976054, 2021). "ABCC3 has been found highly expressed in different types of tumors, and high ABCC3 expression significantly predicted a shorter OS in glioma." (PMID 37334354, 2023). "Previous investigations have indicated the upregulation of ABCC3 (ATP binding cassette subfamily C member 3) in glioma patients." (PMID 37662954, 2023). "To investigate the effect of ABCC3 on glioma cells, we knocked down it in LN299 and U87 cells, respectively." (PMID 35936006, 2022). "Our results also confirmed that ABCC3 attenuated the chemosensitivity of glioma cells to arsenic trioxide." (PMID 36091778, 2022). "The results suggested that the knockdown of ABCC3 elevated the chemosensitivity of glioma cells to arsenic trioxide." (PMID 36091778, 2022). "In the present research, our team intended to explore the expression and clinical significance of ABCC3 in glioma patients." (PMID 34976054, 2021). "In glioma, ABCC3 was shown to predict reactions in GBM sufferers receiving combined chemo and DC immune therapy." (PMID 34976054, 2021). "Herein, our team offered proofs that the expression of ABCC3 was an independent prognostic marker for overall survival of glioma sufferers." (PMID 34976054, 2021). "Sequential data filtration (survival analyses, independent prognosis analyses, ROC curve analyses, and clinical association analyses) was completed, which gave rise to the determination of the relationship between glioma and the ABCC3 gene." (PMID 34976054, 2021). "Recently, some studies have discovered the dysregulation of ABCC3 in many cancers, including glioma." (PMID 34976054, 2021). "Clinical assays on the foundation of CGGA and TCGA datasets unveiled that ABCC3 expression was distinctly upregulated in glioma and predicted a shorter overall survival." (PMID 34976054, 2021). "Consistent with the results in this article, the poor prognosis predictive role of ABCC3 has been reported not only in acute myeloid leukemia, gastric cancer, pancreatic cancer, and lung cancer but also in gliomas." (PMID 34295296, 2021). "The expression level of ABCC3 in glioma tissues was significantly lower than that in normal brain tissues." (PMID 33562724, 2021). "The expression level of the ABCC3 gene in glioma tissues was lower than that of corresponding normal brain tissues." (PMID 32161779, 2020). "The overall survival (HR=2.8, P<0.05) and disease-free survival rates (HR=2.0, P<0.05) of patients with ABCC3 low expression glioma were significantly higher than those of patients with high expression of ABCC3." (PMID 32161779, 2020). "The expression level of the ABCC3 gene in glioma tissues was lower than that of normal brain tissues, Figure." (PMID 32161779, 2020). "In the CGGA external validation, ABCC3 and POSTN were significantly associated with the OS in almost all the grades of primary and recurrent glioma." (PMID 32725165, 2020). "In the present work, we used bioinformatics analysis to investigate the expression of the ABCC3 gene in glioma, its related signaling pathway and its relationship with prognosis of glioma patients." (PMID 32161779, 2020).
glioma (continued). "As for these 11 prognostic SRGs, ABCC3 and POSTN were significantly associated with almost all subtypes of glioma." (PMID 32725165, 2020). "In patients with glioma, some studies have also identified ABCC3 as a prognostic biomarker using microarray and next generation sequencing." (PMID 32725165, 2020). "Sun and colleagues reported that CNRIP1 expression level inversely correlates with the expression of the gene for ATP binding cassette subfamily C member 3 (ABCC3) in glioma." (PMID 33261012, 2020). "The cancer genome atlas (TCGA) database was used to analyze the differential expression of the ABCC3 gene in human glioma." (PMID 32161779, 2020). "The overall survival (HR=2.8, P<0.05) and disease-free survival rates (HR=2.0, P<0.05) of patients with ABCC3 low expression glioma were significantly higher than those of patients with high expression of ABCC3, Figure." (PMID 32161779, 2020). "Our recent data indicated that ABCC3 is expressed and upregulated in NK cells from glioma-bearing mice treated with TMZ." (PMID 31771235, 2019). "The multidrug resistance protein ABCC3 was described in our previous studies as a marker of NK cell resistance to TMZ in both the GL261 murine glioma model and DENDR1 patients." (PMID 31771235, 2019). "ABCC3 is expressed more in differentiated glioma cells and regulates multidrug resistance, while ABCB1 and ABCC4 are important multidrug resistance factors." (PMID 25605243, 2015). "ABCC3 presents lower expression levels in normal brain than in glioblastoma samples, and its expression increases with glioma tumor grade." (PMID 36585418, 2022). "Furthermore, ABCC3 significantly affected the prognosis of gliomas in the TCGA, CGGA #325, and CGGA #693 cohorts." (PMID 35936006, 2022). "One of these differentially expressed genes, ABCC3, was related to glioma proliferation and TMZ resistance, which may provide new insights into the function and potential therapeutic role of m1A in glioma." (PMID 36437944, 2022). "Furthermore, we found that ABCC3 was significantly associated with temozolomide (TMZ) resistance, and silencing ABCC3 effectively inhibited glioma cell proliferation." (PMID 35936006, 2022). "All the results indicated that ABCC3 significantly affected the proliferation of glioma cells." (PMID 35936006, 2022). "Furthermore, IC50 analysis showed that knockdown of ABCC3 considerably reduced the resistance of glioma cells to TMZ." (PMID 35936006, 2022). "Our findings suggested ABCC3 might participate in the clinical development of glioma and may be a novel biomarker." (PMID 34976054, 2021). "Herein, our team analyzed the clinical feature of glioma patients with ABCC3 expression, finding that differentially expressed ABCC3 was remarkably related to PRS types, histological status, gradations, ages, chemotherapy states, IDH variant, and 1p19q codeletion." (PMID 34976054, 2021). "Our findings suggested ABCC3 exhibited a prognostic value in glioma and may be involved in clinical progression of glioma via complex mechanisms." (PMID 34976054, 2021). "The expression level of ABCC3 gene in glioma was low compared to normal brain tissue." (PMID 32161779, 2020). "Similarly, ABCC3/MRP3 has been observed in high-grade gliomas such as anaplastic astrocytomas (grade III), GBM." (PMID 31878061, 2019). "ABCC3 was remarkably upregulated in the TMZ-resistant glioma cells and promoted glioma proliferation, indicating it might be associated with the poor outcome of GBM receiving standard-of-care for concurrent radiotherapy and TMZ-chemotherapy after surgical resection." (PMID 35936006, 2022). "Finally, we analyzed the relationship between ABCC3 expressions and clinic characteristics of glioma patients, finding that differentially expressing ABCC3 was remarkably related to age, 1p19q codeletion, PRS type, chemo status, grade, IDH mutation status, and histology." (PMID 34976054, 2021). "Overall, our findings suggested ABCC3 might be a novel prognosis marker in glioma." (PMID 34976054, 2021).
glioma (continued). "We also found that the general OS and DFS of patients with ABCC3 overexpression in all kinds of glioma were significantly lower than those of patients with low expression of ABCC3 which indicated that high expression of ABCC3 may act as a poor molecular marker for glioma patients prognosis." (PMID 32161779, 2020). "The results suggested that the expression of ABCC3 in glioma tissues was significantly lower than that of normal brain tissues, suggesting that ABCC3 may play an important role in the occurrence and development of glioma." (PMID 32161779, 2020). "Other mitochondrial genes such as ABCC3, HOXA4, HOXC10, NNMT, and SCNN1B are typically increased in their expression as the grade of glioma and the higher expression of these genes have been associated with poor prognosis in LGG." (PMID 39012280, 2024). "Survival curves for four model genes (ABCC3, EMP3, AL161787.1, and IGFBP2) highlighted IGFBP2 as a significant marker of decreased survival outcomes in glioma patients." (PMID 37928523, 2023). "We found ABCC3 was up-regulated in the TMZ-resistant PDX model, TMZ-resistant LN229 cells, and TMZ-resistant glioma stem cells (GSCs) compared to corresponding controls." (PMID 35936006, 2022). "Recently, ABCC3 has been included in gene signatures (ABCC3, CD44, TNFRSF1A, and MGMT24; ABCC3, SMC4, EMP3, WEE1, and HIST1H2BK44) that classify glioma patients in agreement with therapeutic response to chemotherapeutic agents, including TMZ." (PMID 36585418, 2022). "Along with ABCC3, POSTN (periostin) was also identified to be the important regulator in the tumorigenesis and treatment of glioma." (PMID 32725165, 2020). "The high-grade glioma samples showed significantly higher levels of ABCC3/MRP3 and ABCB1/P-gp in the endothelial cells, but higher levels of ABCC1/MRP1, ABCC3/MRP3 and ABCC5/MRP5." (PMID 31878061, 2019). "Downregulation of ABCG2 expression decreases the chemoresistance of glioblastoma cancer stem cells, and ABCC3 and ABCC5 have been reported to be expressed higher than the other ABCC subfamily members in glioma." (PMID 25605243, 2015). "Previous studies have demonstrated the function of ABCC3, HOXA4, HOXC10, and NNMT in gliomas." (PMID 37334354, 2023). "Likewise, the ABC transporters, MRP1 (ABCC1), MRP3 (ABCC3), and MRP4 (ABCC4), are highly expressed in glioma cells." (PMID 35740330, 2022). "Correlations between the ABCC3, COL6A2 and FAM20A genes and low-grade glioma suggested that these genes might play more complex roles in gliomas." (PMID 35456975, 2022). "Nevertheless, the clinical significance of ABCC3 in glioma has not been investigated." (PMID 34976054, 2021). "However, the known pathway of ABCC3 may not correlate with the development of glioma." (PMID 32161779, 2020).
lung carcinoma (23 papers, 1995 to 2025). "Similarly, elevated ABCC3 expression in lung cancer cells has been associated with reduced sensitivity to chemotherapeutic agents such as methotrexate, doxorubicin, vincristine, etoposide, and cisplatin." (PMID 41304944, 2025). "Our analysis showed that the expression of ABCC3 was positively correlated with global DNA hypermethylation of lung cancer cells." (PMID 34857857, 2021). "For instance, the expression of ABCC3 in patients with nonsmall cell lung cancer was potentially correlated with drug resistance." (PMID 31665503, 2020). "Several reports have shown the expression of high levels of ABCC1 and ABCC3 in lung cancer specimens." (PMID 27649127, 2016). "Several ABC transporters are linked to lung cancer, such as ABCC1, ABCC3, ABCA3 and ABCC5." (PMID 24625834, 2014). "Our microarray analysis results and preliminary lung tissue array study demonstrated that the ABC gene signature, consisting of ABCA4 and ABCA8 together with ABCC3, can discriminate lung AC vs AT and be considering as a novel lung cancer diagnostic biomarker (not published)." (PMID 22369099, 2011). "Our previous observations on lung cancer cells NCI-H460 overexpressing ABC transporter proteins (LRP, ABCB1, BCRP, ABCC1 ABCC2 and ABCC3) confirmed the ability of resveratrol lignans to overcome the resistance to PTX." (PMID 27304668, 2016). "Of them, 6 miRNAs (miR-149, miR-205, miR-375, miR-378, miR-422a and miR-708) and 9 target genes (CEACAM6, CGN, CLDN3, ABCC3, MLPH, ACSL5, TMEM45B, MUC1) were validated by quantitative PCR in an independent cohort of 41 lung cancer patients." (PMID 24625834, 2014). "ABCC3 is a member of the multidrug resistance protein (MRP) subfamily and was shown to be over-expressed in ovarian carcinoma and doxorubicin-resistant lung cancer cell line." (PMID 23285037, 2012).
ovarian carcinoma (20 papers, 1998 to 2023). A malignant neoplasm originating from the surface ovarian epithelium. "The same trend was observed in the in vitro model of ovarian carcinoma cell lines, where the treatments with taxanes caused downregulation of the ABCC3 expression." (PMID 35008510, 2021). "In ovarian cancer, ABCC3 protein is overexpressed in paclitaxel-resistant A2780/PTX cell line in vitro and upregulated on the transcript level in histological HGSC subtype of EOC patients." (PMID 35008510, 2021). "In connection to novel therapeutic strategies in ovarian cancer, novel interactions between olaparib and ABCC3 were found very recently." (PMID 35008510, 2021). "In conclusion, this study revealed the expression profile of three candidate molecules: ABCC3, CPS1, and TRIP6, previously associated with MDR phenomena, in resistant and sensitive ovarian carcinoma cell lines and EOC patients." (PMID 35008510, 2021). "Higher gene expression of ABCC1 and ABCC3 was also found in ovarian cancer patients with unfavourable outcome following debulking surgery and platinum based chemotherapy." (PMID 24124770, 2013). "Our data supports a role for ABCB3, ABCC1, ABCC2, and ABCC3 in ovarian cancer chemoresistance, which is in agreement with previous studies." (PMID 24124770, 2013). "Our results show that HA induces chemoresistance against CBP, and increases the expression of the ABC transporters, ABCB3, ABCC1, ABCC2, and ABCC3 in ovarian cancer cell lines expressing the HA receptor, CD44." (PMID 24124770, 2013). "Other ABC transporters, including ABCB3 (TAP2), ABCC1 (MRP1), ABCC2 (MRP2, cMOAT), and ABCC3 (MRP3), have been shown to be involved in ovarian cancer chemoresistance." (PMID 24124770, 2013). "Thus, ABCC3 seems to be a novel and promising therapeutic target for ovarian carcinomas, where taxanes are usually used." (PMID 35008510, 2021). "ABCC3 is also involved in glutathione transport in ovarian cancer cells." (PMID 35008510, 2021). "Indeed, previous studies showed that suppression of IGF-1R decreases ABCC2 expression and promoted drug sensitivity in human colon cancer cells, and that IGF-1 increased the expression of ABCC1, ABCC2, and ABCC3 in both leukemia cells and ovarian cancer cells." (PMID 33291663, 2020). "Furthermore HA treatment significantly increased the expression of ABC drug transporters (ABCB3, ABCC1, ABCC2, and ABCC3), but only in ovarian cancer cells expressing CD44." (PMID 24124770, 2013). "Interestingly, a recent study revealed that upregulation of HOXC10 in ovarian cancer could promote ABCC3 expression by transcriptional upregulation of β-catenin, resulting in carboplatin resistance." (PMID 37334354, 2023). "Epithelial ovarian cancer tissues have been shown to express other ABC transporters including, ABCC3 (MRP3), ABCC4 (MRP4), ABCB1 as well as other membrane transporters." (PMID 37838788, 2023). "Spearman correlation analysis of individual genes indicated that ABCC3, an efflux pump from the family of multidrug resistance-related transporters, has a strong and significant positive correlation to SLCO4A1 in the ovarian cancer cells (r = 0.75, p < 0.001)." (PMID 36105223, 2022). "We estimated and observed changes in mRNA and protein profiles of ABCC3, CPS1, and TRIP6 in resistant and sensitive ovarian cancer cells and after the treatment of resistant ovarian cancer models with paclitaxel and Stony Brook taxanes in vitro and in vivo." (PMID 35008510, 2021). "We measured the mRNA expression level of ABCC3, CPS1, and TRIP6 in NCI/ADR-RES ovarian carcinoma cell line after 48 h cultivation with paclitaxel (3000 nM concentration), or novel generation taxanes SB-T-121605 and SB-T-121606 (300 nM concentration)." (PMID 35008510, 2021). "In NCI/ADR-RES ovarian carcinoma cell line, we observed the highest level of TRIP6 mRNA followed by CPS1 and ABCC3 mRNA." (PMID 35008510, 2021).
ovarian carcinoma (continued). "In concordance with results observed in the in vitro model of paclitaxel-resistant ovarian carcinoma cell line NCI/ADR-RES, we observed the highest level to be that of TRIP6 mRNA, followed by ABCC3 and CPS1 transcripts in our set of EOC tumors." (PMID 35008510, 2021). "ABCC3 was found to be increased in the histological HGSC subtype of EOC patients, as well as in cell line model of paclitaxel resistance in ovarian cancer (A2780/PTX)." (PMID 35008510, 2021). "The next goal of this study was to assess whether ABCC3, CPS1, and TRIP6 might serve as biomarkers of prognosis, therapeutic response, and survival of ovarian carcinoma patients for improving therapy personalization." (PMID 35008510, 2021). "Our findings provide new evidence that ABCC3 and CPS1 may act as mediators of therapy response in ovarian cancer cells." (PMID 35008510, 2021). "Furthermore, the present findings suggested two networks of SLCO and ABC-transporter coding genes (SLCO2B1/ABCC3 and ABCB2/ABCB3/ABCC3/HER-2) and demonstrated the expression of SLCO1B7 in ovarian cancer samples." (PMID 30131693, 2018). "Nevertheless, it is not known whether deregulation of ABCC3, CPS1 and TRIP6 occurs in different types of paclitaxel-resistant ovarian carcinoma cells or how the deregulation is affected by the action of paclitaxel and novel taxane derivatives." (PMID 35008510, 2021).